XRCC1 (X-ray repair cross complementing 1)
Diseases named in the same sentence as XRCC1 in open-access papers (continued):
Sharing a sentence is not in itself a finding about the gene and the disease.
lung cancer (76 papers, 2005 to 2025). A malignant neoplasm involving the lung. "An extensive analysis conducted in six Eastern European countries showed that the XRCC1 Arg194Trp genotype is associated with a small risk of lung cancer." (PMID 40650316, 2025). "Similar conclusions were observed in previous studies, which confirmed that the XRCC1 Arg194Trp genotype in particular is associated with a low risk of lung cancer, while the Trp194Trp polymorphism of the XRCC1 gene increases this risk." (PMID 40650316, 2025). "The use of machine learning approaches showed promising results in predicting lung cancer based on XRCC1 polymorphisms." (PMID 40650316, 2025). "The study, which included 109 patients diagnosed with lung cancer in the Chinese population, indicated an increased risk of lung cancer for the XRCC1 Trp194Trpgenotype." (PMID 40650316, 2025). "The aim of this study was to assess the role of the single nucleotide polymorphism Arg399Gln in the XRCC1 gene as a factor influencing the risk of lung cancer." (PMID 40650316, 2025). "Extensive research on XRCC1 SNPs has unequivocally established their correlation with tumour risk, treatment response, and survival outcomes in diverse malignancies, including lung cancer and gastric cancer." (PMID 37679817, 2023). "In one study carried out on the Korean population, SNPs within the XRCC1 gene were identified and linked with lung cancer." (PMID 36833174, 2023). "The aim of this study was to evaluate the possible relationship between several common genetic polymorphisms in DNA repair genes (ERCC1, ERCC2 and XRCC1) and the risk of developing RP in lung cancer patients receiving intensity modulation radiated therapy." (PMID 29416669, 2018). "CYP1A1-rs1048943 GG+AG genotype, GSTM1 deletion genotype, mEH-rs1051740 mutant genotype, XRCC1-rs1799782 TT+CT genotype, XRCC1- rs25489 GG genotype showed significant correlations with lung cancer risk increased." (PMID 29212267, 2017). "A total of 19 studies including 3707 advanced lung cancer patients were included in the final analysis of the relationship between the XRCC1 Arg399Gln polymorphism and OS." (PMID 26585370, 2015). "There were 38 eligible studies with a total number of 5360 advanced lung cancer patients, qualified for the final analysis for the XRCC1 Arg399Gln polymorphism." (PMID 26585370, 2015). "Three studies with a total number of 721 advanced lung cancer patients were enrolled in the final analysis of the association between XRCC1 Arg194Trp polymorphism and median PFS." (PMID 26585370, 2015). "A dysregulation of XRCC1, among a number of other targets, was found to be associated with higher prevalence of lung cancer." (PMID 25800737, 2015). "Four studies including 349 advanced lung cancer patients were finally included in this part of analysis for the XRCC1 Arg399Gln polymorphism." (PMID 26585370, 2015). "We are delighted to find that the XRCC1 Arg194Trp and Arg399Gln polymorphisms are significantly associated with clinical outcomes in advanced lung cancer patients treated with platinum-based chemotherapy." (PMID 26585370, 2015). "In an analysis of 103 patients with stage IIIA–IV lung cancer, those with one or two variant alleles at XRCC1 (Arg399Gln) or XPD (Asp312Asn) showed poorer OS compared with those carrying homozygous wild-type alleles (P = 0.07 and P = 0.003, respectively)." (PMID 25374063, 2015). "There were six studies, altogether 1056 advanced lung cancer patients, finally qualified for the analysis of the association between XRCC1 Arg399Gln polymorphism and median PFS." (PMID 26585370, 2015).
lung cancer (continued). "In conclusion, despite the limitations, our meta-analysis indicates a predictive role for the genetic polymorphisms of XRCC1 gene in clinical outcomes of platinum-based chemotherapy for advanced lung cancer patients." (PMID 26585370, 2015). "Five studies including 1559 advanced lung cancer patients were eligible for the final analysis of the relationship between the XRCC1 Arg194Trp polymorphism and OS." (PMID 26585370, 2015). "Later on, many molecular epidemiological studies reported the association of XRCC1 Arg194Trp with lung cancer susceptibility." (PMID 24590265, 2014). "X-ray repair cross-complementing group 1 (XRCC1) gene Arg194Trp polymorphism has been reported to be associated with risk of lung cancer in many published studies." (PMID 24590265, 2014). "In conclusion, this meta-analysis indicates that XRCC1 −77T>C shows an increased lung cancer risk and XRCC3 T241M polymorphism is associated with decreased lung cancer risk, especially in Caucasians." (PMID 23990873, 2013). "In conclusion, this meta-analysis indicates that XRCC1 −77T>C shows an increased lung cancer risk and XRCC3 T241M polymorphism is associated with decreased lung cancer risk in Caucasians." (PMID 23990873, 2013). "The XRCC1 399Arg/Gln genotype has been reported to be associated with radiation sensitivity, mutagen sensitivity and risk for lung cancer." (PMID 23375119, 2013). "For example, genetic aberrations in genes for matrix metalloproteinase (MMP) -3 and MMP-9 or the x-ray repair protein XRCC1 have been reported to influence the clinical behavior and risk of metastasis of lung cancer." (PMID 23840350, 2013). "Overall, our meta-analysis indicates that XRCC1 −77T>C polymorphism is associated with increased lung cancer risk when all eligible studies were pooled into the meta-analysis." (PMID 23990873, 2013). "Variant genotypes of XRCC1 399 polymorphism were associated with higher risks of death for lung cancer patients." (PMID 22339849, 2012). "XRCC1 Arg194Trp and Arg399Gln polymorphisms were significantly associated with response to treatment in lung cancer patients." (PMID 22339849, 2012). "There have been previous studies investigating possible associations between XRCC1 SNPs and chemotherapy outcomes or overall survival of lung cancer." (PMID 22339849, 2012). "This meta-analysis aimed to summarize published data on the association between the commonest SNPs of XRCC1 (Arg194Trp, C > T, rs1799782 and Arg399Gln, G > A, rs25487) and clinical outcome of lung cancer patients." (PMID 22339849, 2012). "Some studies have reported the relationship between polymorphisms in XRCC1 gene and clinical outcome or overall survival of lung cancer patients, however the results were inconsistent." (PMID 22339849, 2012). "Single nucleotide polymorphisms (SNPs) of XRCC1 are suspected to have some relationship with response to chemotherapy and overall survival of lung cancer." (PMID 22339849, 2012). "Several papers have investigated the association between lung cancer and genetic polymorphisms in XRCC1, suggesting a predisposition to lung cancer development for the patients carrying these gene alterations." (PMID 18793406, 2008). "The association between the XRCC1 Arg399Gln polymorphism, resulting from a guanine to adenine nucleotide change, and lung cancer risk has been evaluated in a number of epidemiological studies." (PMID 17705814, 2007). "The results of the present study are generally consistent with previous findings in a relatively large lung cancer study, which showed a protective effect of the XRCC1 194Trp allele against tobacco-related lung cancers (OR = 0.86; 95% CI, 0.77 – 0.95)." (PMID 16796765, 2006). "Moreover, the presence of single nucleotide polymorphism (SNP)-77 T > C in the 5′-untranslated region (UTR) of XRCC1 is associated with an increased risk of developing lung cancer." (PMID 34486486, 2021).
lung cancer (continued). "The upstream signaling molecule of ADCY1 such as forskolin, an activator of ADCY1, can stimulate ADCY1 to catalyze cAMP, can inhibit DNA damage, DNA repair and cell apoptosis which is caused by the degradation of XRCC1 in an Epac-dependent pathway in lung cancer cells." (PMID 31839819, 2019). "The expression and polymorphisms of XRCC1 play an important role in DNA repair and it may be a prognosis biomarker for lung cancer patients treated with radiation or chemotherapy." (PMID 31839819, 2019). "Similarly, Peng and colleagues demonstrated that nonsmall-cell lung cancer patients treated with platinum-based chemotherapy and carrying at least one variant allele of XRCC1 p.Arg399Glu had increased risk of hematological toxicity grade 3–4." (PMID 29507678, 2018). "The publication bias in the enrolled studies on the association of the XRCC1 Arg194Trp and Arg399Gln polymorphisms with clinical outcomes of advanced lung cancer patients treated with platinum-based chemotherapy was assessed by the Begg’s funnel plot and Egger’s test." (PMID 26585370, 2015). "No other significant differences were detected with respect to the associations between predictive assessment in pharmacogenetics of XRCC1 genetic polymorphisms and the clinical outcomes of advanced lung cancer patients treated with platinum-based chemotherapy." (PMID 26585370, 2015). "Our cumulative meta-analyses based on year of publication indicated that there was a distinct trend toward a better response rate to platinum-based chemotherapy treatment with advanced lung cancer patients for the XRCC1 Arg194Trp polymorphism (TrpTrp+TrpArg vs. ArgArg)." (PMID 26585370, 2015). "Because the data from these enrolled studies on the association of XRCC1 Arg399Gln polymorphism with median TTP was too insufficient to be conducted meta-analysis, we only summarized the general predictive value of the median TTP for XRCC1 Arg399Gln polymorphism in advanced lung cancer patients." (PMID 26585370, 2015). "Importantly, the previous meta-analyses on XRCC1 Arg194Trp, Arg280His, and Arg399Gln with lung cancer risk have shown conflicting conclusions." (PMID 23990873, 2013). "Their meta-analysis had demonstrated that codon 194, codon 399 and −77 T>C polymorphisms of XRCC1 gene might have contributed to individual susceptibility to lung cancer." (PMID 23990873, 2013). "Their results indicated that certain XRCC1 codon 399 and 194 variant may affect the susceptibility of lung cancer." (PMID 23990873, 2013). "The DNA repair capacity may associate with the risk of chromium exposure induced disease such as lung cancer and XRCC1 Arg399Gln could be served as a genetic biomarker of susceptibility for chromium exposure." (PMID 22642904, 2012). "Lung cancer patients with XRCC1 194 T allele or XRCC1 399 G allele may benefit from platinum-based chemotherapy." (PMID 22339849, 2012). "Genetic polymorphisms in XRCC1 gene might be associated with overall survival and response to platinum-based chemotherapy in lung cancer patients." (PMID 22339849, 2012). "In conclusion, our meta-analysis suggested that XRCC1 Arg194Trp and Arg399Gln polymorphisms may be associated with overall survival and response to platinum-based chemotherapy in lung cancer patients." (PMID 22339849, 2012). "Previous reports have also suggested that XRCC1 polymorphisms might be risk factors for the development of lung cancer and promising predictive or prognostic makers for lung cancer patients." (PMID 22339849, 2012). "Thus, we suggested that the XRCC1 Arg194Trp and Arg399Gln genetic polymorphisms may be predictive factors for treatment response to advanced lung cancer patients treated with platinum-based chemotherapy." (PMID 26585370, 2015). "More recently, the circRNA circFLNA has been found to promote lung cancer progression by acting as a sponge of miR-486-3p and thus regulating the XRCC1 (X-ray Repair Cross Complementing 1) and CYP1A1 (Cytochrome P450 Family 1 Subfamily A Member 1) genes." (PMID 38501058, 2024).
lung cancer (continued). "In a separate study, SIRT1 inhibited proteasomal degradation of XRCC1, leading to cisplatin resistance in lung cancer cell lines." (PMID 38659583, 2024). "Polymorphisms in two DNA repair genes, XRCC1 and HOGG1, have been reported to increase the risk of both lung cancer and NPC." (PMID 37718438, 2023). "The results in this study revealed that circFLNA acted as a sponge of miR-486-3p to promote the proliferation, migration, and invasion of lung cancer cells via regulating XRCC1 and CYP1A1 in vitro and in vivo." (PMID 33500536, 2022). "In conclusion, circFLNA acted as a sponge of miR-486-3p to promote the proliferation, migration, and invasion of lung cancer cells in vitro and in vivo by regulating XRCC1 and CYP1A1." (PMID 33500536, 2022). "XRCC1 is an important factor participating in repairing DNA damage and contributes to chemoresistance in serious cancers such as liver and lung cancers." (PMID 33500536, 2022). "Further, ADCY1 catalyzes the elevation of cAMP and consequently inhibits the EPAC-dependent pathway degradation of XRCC1-induced DNA damage, DNA repair, and apoptosis in lung cancer cells." (PMID 35832555, 2022). "In lung cancer, ADCY1 can modulate anticancer drugs and regulate apoptosis by regulating the expression of Bcl-2 family proteins, IAPs, and XRCC1 in human lung cancer cells." (PMID 35832555, 2022). "XRCC1 and COMT gene polymorphisms and COFs exposure are central risk factors in the progression of lung cancer." (PMID 34837917, 2021). "cAMP signaling inhibited repair of gamma radiation-induced DNA damage via enhancing degradation of XRCC1 in lung cancer cells." (PMID 34512699, 2021). "In lung cancer cells cAMP through EPAC action inhibits the repair of γ-ray-induced DNA damage by the degradation of X-ray repair cross-complementing protein 1 (XRCC1)." (PMID 32854274, 2020). "It has been widely acknowledged that cAMP can regulate cell apoptosis by modulating the expression of Bcl-2 family proteins, the inhibitor of apoptosis proteins (IAPs) and the repair protein (XRCC1) of γ-ray-induced DNA damage in human lung cancer cells." (PMID 31839819, 2019). "Here, we describes SIRT1 confers chemoresistance to lung cancer cells by deacetylating and stabilizing XRCC1." (PMID 31043584, 2019). "Previous studies have reported that XRCC1 expression is elevated in colorectal, esophageal, and lung cancer tissues." (PMID 30408066, 2018). "Seven studies including 1208 individuals referred the predictive value of XRCC1 Arg194Trp with respect to the sensitivity of lung cancer to platinum-based treatment." (PMID 28743242, 2017). "Another study demonstrated that enhancement of the cytotoxicity to cisplatin by administration of curcumin, an anti-inflammatory molecule in the turmeric root, is mediated by the downregulation of the expression levels of XRCC1 in human lung cancer cells." (PMID 29117108, 2017). "The XRCC1 Arg194Trp and Arg399Gln polymorphisms are likely to be associated with the ORR, OS and sensitivity to platinum-based chemotherapy for advanced lung cancer patients." (PMID 26585370, 2015). "Therefore, findings from this study could provide more precise and reliable comprehensive assessment than those published meta-analyses on the predictive role of XRCC1 genetic polymorphisms in clinical outcomes of platinum-based chemotherapy treatment for advanced lung cancer patients." (PMID 26585370, 2015). "Letkova and his colleagues investigated the polymorphisms of selected DNA repair genes, including XPC, XPD, hOGG1 and XRCC1, and found the different risks of developing lung cancer when stratified by gender, which further supporting our current findings." (PMID 26228655, 2015). "For example, polymorphisms in two DNA repair genes, XRCC1 and HOGG1, have been reported to increase the risk of both lung cancer and NPC." (PMID 26376733, 2015).
lung cancer (continued). "Thus, it is speculated that the functional SNPs in XRCC1 gene might be associated with sensitivity to platinum-based anticancer drugs and have predictive or prognostic values in clinical outcomes for patients with lung cancer." (PMID 26585370, 2015). "Although several studies previously performed pooling analyses regarding the association of XRCC1 Arg399Gln, Arg194Trp, Arg280His, −77T>C, and XRCC3 T241M with lung cancer risk." (PMID 23990873, 2013). "To unravel its genetic underpinnings, we sought to investigate the association of three well-characterized nonsynonymous polymorphisms in XRCC1 (Arg194Trp and Arg399Gln) and XRCC3 (Thr241Met) genes with lung cancer risk in northeastern Chinese." (PMID 23409158, 2013). "In this study, we sought to investigate the association of three well-characterized nonsynonymous polymorphisms in XRCC1 and XRCC3 genes with lung cancer in northeastern Chinese." (PMID 23409158, 2013). "By far, several meta-analyses have summarized the predisposition of XRCC1 and XRCC3 genetic polymorphisms to lung cancer." (PMID 23409158, 2013). "Many molecular epidemiological studies have reported the role of XRCC1 Arg399Gln, Arg194Trp, Arg280His, −77T>C, and XRCC3 T241M in lung cancer risk, but the results remain conflicting rather than conclusive." (PMID 23990873, 2013). "In order to explore the association between XRCC1 Arg399Gln, Arg194Trp, Arg280His, −77T>C, and XRCC3 T241M polymorphisms with lung cancer risk, a meta-analysis was conducted to summarize the data." (PMID 23990873, 2013). "The previous studies also point out to the relation of XRCC1 (Arg399Gln, Arg194Trp) and XRCC3 Trp241Met polymorphisms with colorectal cancer, skin cancer, lung cancer, and others." (PMID 23675381, 2013). "Our study significantly demonstrated an independent and synergistic contribution of XRCC1 Arg399Gln and XRCC3 Thr241Met polymorphisms to lung cancer susceptibility in northeastern Chinese." (PMID 23409158, 2013). "Taken together, our study significantly demonstrated an independent and synergistic contribution of XRCC1 gene Arg399Gln and XRCC3 gene Thr241Met polymorphisms to lung cancer susceptibility in northeastern Chinese." (PMID 23409158, 2013). "Molecular epidemiological studies have reported the association of XRCC1 Arg399Gln, Arg194Trp, Arg280His, −77T>C, and XRCC3 T241M with lung cancer risk, but the results remain conflicting rather than conclusive." (PMID 23990873, 2013). "So we performed a systemic review and meta-analysis to assess the evidence about effects of XRCC1 SNPs on the efficacy of chemotherapy and overall survival in lung cancer patients." (PMID 22339849, 2012). "Four studies including 371 patients were used to analyze the relationship of the combinations between XRCC1 Arg194Trp and Arg399Gln genotypes with the objective response in lung cancer patients." (PMID 22339849, 2012). "We showed, by an extensive quantitative and systematic review of published reports, that XRCC1 194 C/T and XRCC1 399 G/A SNPs were associated with objective response and XRCC1 399 G/A genotype and A/A genotype could influence overall survival of lung cancer patients." (PMID 22339849, 2012). "In conclusion, we analysed the association between XPC, XPD, XRCC1, and XRCC3 polymorphisms and the individual susceptibility to develop lung cancer in the Spanish population, specifically with a highly tobacco exposed population." (PMID 17705814, 2007). "We investigated the relationship between polymorphisms in two NER genes, XPC (poly (AT) insertion/deletion: PAT-/+) and XPD (Asp312Asn and Lys751Gln), the BER gene XRCC1 (Arg399Gln), and the DSBR gene XRCC3 (Thr241Met) and the risk of developing lung cancer." (PMID 17705814, 2007). "It was shown that the change in the XRCC1 399Gln/Gln gene variant to XRCC1 Arg399Gln was associated with an increased risk of lung cancer among Asians, but not among Caucasians." (PMID 40650316, 2025).